NRAS (NRAS proto-oncogene, GTPase)
Diseases named in the same sentence as NRAS in open-access papers (continued):
Sharing a sentence is not in itself a finding about the gene and the disease.
melanoma (continued). "Binimetinib is an allosteric selective, ATP-non-competitive inhibitor of MEK1/2 that demonstrated anti-tumoral activity by abrogating the growth of NRAS- and V600E BRAF-mutated melanomas in preclinical studies using in vitro and in vivo models." (PMID 29455659, 2018). "Using the TCGA skin cutaneous melanoma dataset and biopsies from 54 patients to search for new targets to treat NRAS‐mutant melanoma, the authors discovered that BRD4 expression was significantly elevated in tumor cells and correlated with poor survival." (PMID 29661909, 2018). "Treatment of NRAS-mutant melanoma cells with 6-thio-dG led to cell death after 7–14 days, without evidence for significant telomere shortening after 14 days." (PMID 29695835, 2018). "We next tested the performance of Calabrese in another cell line, MelJuSo, a BRAF-wildtype, NRAS-mutant melanoma line engineered to express dCas9-VP64." (PMID 30575746, 2018). "Our studies support the notion that NRAS-mutant melanoma is a prime candidate for TERT-based therapeutic approaches." (PMID 29695835, 2018). "Treatment of NRAS‐mutant melanoma cells with a single dose of JQ‐1 (0.5 μM) in combination with PD901 (0.1 μM) substantially impaired colony formation compared to single agent treatment (Fig EV3B)." (PMID 29650805, 2018). "Metastatic melanomas are subdivided by their mutation profile into four subtypes BRAF driven (about 52%), NRAS driven (28%), Neurofibromin 1 (NF1) mutated (14%) and in “triple wild type”." (PMID 30360441, 2018). "We reviewed cell line response data and confirmed that both oncogenic BRAF and NRAS predict sensitivity to MEK inhibition in melanoma." (PMID 30237495, 2018). "Combined treatment with JQ1 or OTX‐015 plus PD901 triggered substantial cell death of NRAS‐mutant melanoma spheroids, compared to vehicle or single agent treatments." (PMID 29650805, 2018). "Combining trametinib with the clinically relevant BETi OTX‐015 more potently induced cell death compared to single agents, further supporting the notion that the combination of BET and MEK inhibitors elicit cytotoxic effects in NRAS‐mutant melanoma." (PMID 29650805, 2018). "To identify specific vulnerabilities of NRAS-mutant melanoma, we performed gene expression analysis in NRAS-mutant melanoma cells following depletion of NRAS." (PMID 29695835, 2018). "Ectopic expression of wild-type (WT) TERT, or either of the two catalytically impaired TERT mutants, FVYL1016 or FVYL1028, partially protected melanoma cells from cell death induced by NRAS depletion." (PMID 29695835, 2018). "The BRAF mutations are present in about 40–50%, mutations of NRAS in 20% and of c-KIT in 1–3% of the melanomas." (PMID 30360441, 2018). "Compared with BRAFWT and NRASWT melanoma, significantly higher DUSP6 expression was found in melanoma cells with BRAF and NRAS mutations." (PMID 30577494, 2018). "Not surprisingly, the S210L mutation in APT1 is observed at a much lower frequency compared to well-established oncogenes frequently mutated in melanoma, such as BRAF or NRAS." (PMID 29648538, 2018). "Here we used NRAS-mutant melanoma as a treatment refractory model to investigate the therapeutic value of exploiting melanoma’s addiction to TERT, and activation of adaptive mechanisms limiting the effects of TERT-based approaches." (PMID 29695835, 2018). "Despite no clear association in TCGA cases between KMT2D and conventional subtypes of melanoma such as NRAS or BRAF, a subsequent study showed that KMT2D deregulates specific enhancers and genes in NRAS-mutant melanoma." (PMID 30466474, 2018). "The anti-proliferative effects of both SR4 and niclosamide were evaluated in melanoma cells with wild type BRAF (Mewo, SK-MEL-2), BRAFV600E (A101D, A375, A2058, SK-MEL5, SK-MEL-28) and NRAS (SK-MEL-2) mutations using the Cell Titer Glo cell viability assay." (PMID 30651927, 2018). "The tumor suppressor gene PTEN is the third most frequently mutated gene in melanoma after BRAF and NRAS and promotes cell survival." (PMID 29946532, 2018).
melanoma (continued). "Here the authors show that Usp9x regulates the stability of the transcription factor Ets-1 that in turn impacts metastatic melanoma through increased expression of NRAS." (PMID 28198367, 2017). "The TCGA network (The Cancer Genome Atlas Network) has now established a classification of cutaneous tumors according to their mutational status for genes BRAF, NRAS and NF1, all known as major actors of tumor initiation for melanoma." (PMID 29081790, 2017). "Paradoxically, CRAF but not BRAF was shown to be critical for various RAS-driven cancers, raising the question of the role of RAF proteins in NRAS-induced melanoma." (PMID 28497782, 2017). "Confirming the screen results, varying concentrations of ganetespib increased the sensitivity of 2549 and 2338, and additional human melanoma cell lines 2400 and 2559 (BRAF V600E mutated), 2812 (wild type for BRAF, NRAS and cKIT) to T-cell-mediated killing." (PMID 28878208, 2017). "Similar enhanced anti-tumor combination activity was observed in a BRAF mutant (A375.X1) and NRAS mutant (IPC-298) melanoma model, suggesting the potential for application of this combination strategy in other MAPK-dysregulated settings." (PMID 28982154, 2017). "Some studies found no prognostic impact of mutation status and other studies demonstrated that BRAF-mutant or NRAS-mutant melanoma patients had poorer overall survival." (PMID 29349077, 2017). "Two human melanoma cell lines 2549 (wild type for BRAF, NRAS and cKIT) and 2338 (BRAF V600E mutated) were treated with 1 μM of each compound for 24 h, or DMSO as a control." (PMID 28878208, 2017). "This work enabled us to propose a model highlighting the respective roles of RAF kinases during NRAS-induced melanoma progression." (PMID 28497782, 2017). "We show that BRAF expression is required for ERK activation and nevi development, demonstrating a critical role in the early stages of NRAS-driven melanoma." (PMID 28497782, 2017). "Mutations in the BRAF (B-Raf proto-oncogene, serine/threonine kinase) and NRAS (neuroblastoma rat sarcoma viral oncogene) have been identified as key drivers in melanoma progression." (PMID 28522871, 2017). "Our results are consistent with the notion that in addition to activation of the MAPK pathway by mutations of BRAF or NRAS in roughly 60% of melanoma patients, also over-activation of the FGF axis contributes to melanoma growth." (PMID 29152117, 2017). "As an example of this nuance, in melanoma the hot-spot V600 and K601 BRAF mutations are significantly exclusive from NRAS hot-spot mutations." (PMID 29118384, 2017). "Somatic mutations in many cancers including colon carcinoma, melanoma, or pancreatic cancer are often found in BRAF, KRAS, or NRAS." (PMID 28537899, 2017). "Binimetinib showed clinical activity in a phase 2 study (NCT01320085), yielding a 15% response rate in patients with advanced NRAS-mutant melanoma." (PMID 28152546, 2017). "RAC1 mutations are present in all melanoma subtypes, which can be explained by its position at the crossroads of KIT/NRAS/BRAF/MAPK signaling and the PI3K/PTEN/AKT axis." (PMID 28265786, 2017). "Twelve out of 71 (16.9%) mucosal melanomas analyzed harbored RAS mutations, 8 in the NRAS and 4 in the KRAS gene." (PMID 28380455, 2017). "Although inhibition of ERK1/2 mostly reduced cell growth of BRAF mutant melanomas, it also showed some partial reduction in NRAS and KRAS mutant cancer cell growth." (PMID 29180761, 2017). "MEK1/2 inhibitors such as trametinib have been shown to be active in BRAF/NRAS wild type melanomas and induced at least a partial response in 10% of melanoma patients." (PMID 27903987, 2017). "Mutant NRAS melanomas have been reported to have more aggressive clinical features than other subtypes, with thicker lesions, elevated mitotic activity, and higher rates of lymph node metastasis." (PMID 28668077, 2017).
melanoma (continued). "Even though the mutational status was not a consistent risk factor for OS in multivariate analysis, our results suggest that NRAS-mutant tumors tend to behave more aggressively than their BRAF-mutant and WT counterparts in a high-risk melanoma population." (PMID 28797232, 2017). "As such, routine genetic testing of melanoma patients for TERT promoter mutations in addition to mutant BRAF and NRAS would be clinically beneficial." (PMID 29108273, 2017). "In this study, we assessed the presence of SDHD promoter mutations and SDHD protein expression in CM, OM and in melanoma cell lines, in which we already determined BRAF, NRAS, GNAQ and TERT promoter mutational status." (PMID 28662141, 2017). "Mutations in BRAF, NRAS, or KIT are present in more than 60% of melanoma cases, but a useful blood-based biomarker for the clinical monitoring of melanoma patients is still lacking." (PMID 28484715, 2017). "Given the high prevalence of the TERT promoter mutations C228T and C250T in cutaneous melanoma, their addition to existing tests for detection of mutant BRAF and NRAS will allow monitoring of most melanoma patients using ddPCR." (PMID 29108273, 2017). "In advanced melanoma, for example, phase II and III studies showed that NRAS-mutated tumors respond to MEK inhibitors alone." (PMID 28537899, 2017). "In a previous study of combined lung cancer, colorectal cancer and melanoma specimens, kinase-impaired BRAF mutants were associated with a higher incidence of a concomitant activating KRAS/NRAS mutation." (PMID 29228562, 2017). "We have also developed an investigator-initiated Phase IA/B clinical trial using this new formulation of MBZ in combination with a MEK inhibitor for patients with NRAS mutant melanoma that is currently under review at a major pharmaceutical company." (PMID 28157711, 2017). "Here, using conditional ablation of Raf genes in NRAS-induced mouse melanoma models, we investigate their contribution in tumour progression, from the onset of benign tumours to malignant tumour maintenance." (PMID 28497782, 2017). "In the subsequent phase 3 NEMO study (NCT01763164), binimetinib met its primary endpoint, conferring significantly longer PFS vs dacarbazine in patients with NRAS-mutant melanoma." (PMID 28152546, 2017). "Here, we show that the EPE peptide not only reduces the growth of many BRAF mutant melanomas, but also several NRAS and NF1 mutant melanomas, insensitive to BRAF inhibition." (PMID 29180761, 2017). "Clinical trials showed that inhibitors of MEK1/2, downstream of the RAS pathway, had promising efficiency in KRAS mutant NSCLC and NRAS mutant melanoma." (PMID 29285234, 2017). "For melanoma cell lines, the preeminent factors are the presence of the most significantly mutated genes (BRAF, NRAS, NF1, or triple wild type) and proliferative or invasive behavior (MITF/AXL expression ratio)." (PMID 29383127, 2017). "Excitingly, these results were observed even in the melanomas that have relapsed from molecular-targeted or immune-therapies and also those with varying genetic backgrounds (wild type or mutated for BRAF, NRAS, or NF1)." (PMID 27086916, 2017). "In light of the relative non-toxicity of MBZ, we propose that the MBZ-trametinib combination is a compelling candidate as a therapeutic for patients with metastatic NRAS mutant melanoma." (PMID 28157711, 2017). "As one of the RAS oncogene family, NRAS have been reported to be involved in development of leukemia, melanoma and glioma." (PMID 29033691, 2017). "TAK-632 was shown to induce minimal paradoxical activation and potent antiproliferative effects in preclinical NRAS- and BRAF-mutated melanoma models." (PMID 28002790, 2017). "We noted that melanoma was unexpectedly dependent on Usp9x for 3D growth and in vivo expansion, with potential Usp9x addiction noted in NRAS mutant melanoma." (PMID 28198367, 2017).
melanoma (continued). "We did not confirm these results in our study, since our three patients with NRAS mutant melanoma all had PD as BOR." (PMID 29157311, 2017). "Among the mutations involved in melanoma pathogenesis, those repeatedly identified from BRAF and NRAS oncogenes have been investigated." (PMID 29229974, 2017). "To define a mechanism for regulation of NRAS expression by Usp9x in melanoma, we examined the effect of Usp9x (or Ets-1) on NRAS promoter activity." (PMID 28198367, 2017). "Our findings likely explain the observation of enhanced efficacy with dual MEK ERK inhibition in NRAS mutant melanoma cell lines." (PMID 28982154, 2017). "RAS activating mutations occur in 30 % of all cancers, including a high prevalence in melanoma (15–25 %), with KRAS mutations more common in adenocarcinomas and solid tumors and NRAS mutations more common in leukemia, thyroid carcinoma, and malignant melanoma." (PMID 27650277, 2017). "NRAS-mutant melanoma patients showed a significantly higher portion of nodal relapse and the shortest time to loco-regional nodal relapse." (PMID 28797232, 2017). "One report demonstrated that patients with NRAS mutant metastatic melanoma achieved increased clinical benefit from ipilimumab compared to patients with BRAF/NRAS wild type melanomas." (PMID 29157311, 2017). "Examples of actionable mutations include RAS (KRAS and NRAS), BRAF and PI3 K in colorectal cancer, BRAF or NRAS as well as KIT in malignant melanoma, and others." (PMID 28137276, 2017). "The second most common type of driver mutations in melanomas occur in NRAS (neuroblastoma RAS viral v-ras oncogene) and are found in 15–20% of melanoma patients." (PMID 29276510, 2017). "A recent study based on 213 human melanoma samples identified three frequently mutated genes: BRAF, NRAS and NF1, with frequencies of 38.5, 28.6 and 12.2%, respectively." (PMID 28637487, 2017). "Regarding melanoma, our findings establish that BRAF not only plays an obvious key role in BRAF-mutated tumours, but is also essential for NRAS-induced tumours." (PMID 28497782, 2017). "In this study we observed a dominant role for the HGF/MET axis in mediating resistance to BRAF and MEK inhibitors in models of BRAFV600E and NRAS mutant melanoma." (PMID 28147313, 2017). "β-catenin signaling decreased the migration of melanocytes and melanoma cell lines in vitro but promoted lung metastases in the NRAS-driven melanoma murine model." (PMID 28476164, 2017). "We applied microfluidic single-cell RNA-seq to measure the transcriptome of 92 single cells obtained from a BRAF/NRAS wild type melanoma short-term culture (Ma-Mel-123)." (PMID 27903987, 2017). "Both Usp9x and Ets-1 KD consistently and effectively suspended 3D growth of NRAS mutant melanoma derived from metastatic lesions." (PMID 28198367, 2017). "To determine this, we simultaneously knocked down the expression of E2F2 and IFI6 using shRNA and observed a significant rescue of the NRAS-mutant melanoma cell's ability to form colonies in soft agar and tumors in mice." (PMID 27608486, 2016). "We found that α-Mangostin significantly enhances Sorafenib pharmacological efficacy against an NRAS mutant melanoma cell line." (PMID 27152946, 2016). "This mitochondrial control of ER stress-mediated cell death is similar in both BRAF- and NRAS-mutant melanoma cells exposed to MEK inhibitors." (PMID 27250023, 2016). "To date, there are no Food and Drug Administration (FDA) approved targeted therapies for NRAS mutant melanoma patients." (PMID 27447557, 2016). "Human melanomas (n = 17) of different genotypes (mutated BRAF, NRAS, amplified cKIT and wild type) were successfully engrafted in mice then amplified by successive transplantations." (PMID 26909610, 2016). "The selected cell line's mutations represented melanoma - eight CDX samples originated from BRAF mutant melanoma, SK-MEL-2 harbored an activating Q61R NRAS mutation and MeWo carried multiple NF1 inactivating mutations." (PMID 27009863, 2016).
melanoma (continued). "NRAS-mutant melanoma were significantly more resistant to the cytotoxic effects of DNA replication stress-inducing drugs, and knockdown of IFI6 increased sensitivity to these drugs." (PMID 27608486, 2016). "The computational approach here detected notable differences in the immune-cell networks between BRAF and NRAS mutated metastatic melanomas, in addition to BRAF mutated melanomas that have acquired resistance after combined MAPKi therapy." (PMID 27377892, 2016). "We demonstrated that, in BLM (BRAF-wild type, NRAS-mutant) melanoma cells, ERβ agonists [17β-estradiol, diarylpropionitrile (DPN), KB1] significantly inhibited cell proliferation, and this effect was abrogated by an ER antagonist." (PMID 27833586, 2016). "Surprisingly, we also found that NRAS-mutant melanoma cells were significantly more resistant to the drugs that induce DNA replication stress than were BRAF-mutant, NF1-deficient, or triple wild-type melanomas." (PMID 27608486, 2016). "In parallel to “genetic” resistance to MAPKi, due to the acquisition of genetic mutations, affecting NRAS or MEK, the present study emphasizes melanoma cell plasticity as a potent driver of “phenotypic” resistance." (PMID 27596438, 2016). "Recently, genetic subsets of melanoma have been characterized, especially with known driver mutations such as BRAF, NRAS, GNAQ, RAC1, C-KIT, and others." (PMID 26871475, 2016). "Toward this end, we sought to identify factors that are necessary for oncogenic NRAS-induced melanocyte transformation and melanoma growth." (PMID 27608486, 2016). "Melanoma is a heterogeneous tumor, with most patients harboring mutations in the BRAF or NRAS oncogenes, leading to the overactivation of the MAPK/ERK and PI3K/Akt pathways." (PMID 27833586, 2016). "Towards finding new pharmacological strategies that overcome NRAS mutant melanoma, we performed a cell proliferation-based combination screen using a collection of well-characterized small molecule kinase inhibitors and α-Mangostin." (PMID 27152946, 2016). "Recently published studies showed that mutant NRAS melanoma and neuroblastoma cells are highly sensitive to the combination of MEK and combined PI3K/mTOR inhibitors which are in preclinical or early clinical development." (PMID 26821351, 2016). "For instance, Ras/Raf/Mek signalling has come to the fore with the finding that up to 50% of melanomas have a BRAF mutation and up to 30% have a NRAS mutation, with resulting inhibitors targeting BRAF specifically and MEK signalling in general." (PMID 27384486, 2016). "Respectively 50%, 30%, 33% and 20% of BRAF-, NRAS-, c-KIT-mutated or wild type melanomas were successfully engrafted." (PMID 26909610, 2016). "We found that cytotoxic agents that typically inhibit growth by inducing DNA replication stress are largely ineffective at inhibiting NRAS-mutant melanomas." (PMID 27608486, 2016). "Collectively, we demonstrate that IFI6, via E2F2 regulates DNA replication and melanoma development and growth, and this pathway can be pharmacologically targeted to inhibit NRAS-mutant melanoma." (PMID 27608486, 2016). "One study demonstrated a synergistic relationship between metformin and vemurafenib in 7/8 BRAF wild-type/NRAS mutant melanoma cell lines tested." (PMID 27447557, 2016). "In general, mutations in position 16 and 102 can be seen as a signature of two types of cancer: colorectal, characterized by KRAS G12, and melanoma, characterized by NRAS Q61." (PMID 26860319, 2016). "We therefore performed a drug combination screening of α-Mangostin with a collection of compounds containing known-target kinase inhibitors, against SK-MEL-2, a NRAS mutant melanoma cell line." (PMID 27152946, 2016). "Because MITF is crucial for the survival of the melanocyte lineage, we argued that it would also be relevant for NRAS mutant melanoma cell survival." (PMID 26977879, 2016).